EGFR (epidermal growth factor receptor)
Diseases named in the same sentence as EGFR in open-access papers (continued):
Sharing a sentence is not in itself a finding about the gene and the disease.
metastatic disease (continued). "In the future, more attention should be paid to EGFR mutations and ALK rearrangements in primary and metastatic tumors to allow for accurate diagnosis and personalized, precise medication in clinical practice." (PMID 33285759, 2020). "In metastatic tumors, EGFR overexpression was more frequently detectedas a consequence of gene amplification or a high frequency of polysomies." (PMID 32170146, 2020). "In those with metastatic disease, the treatment repertoire has been extended to include biologically targeted agents, including monoclonal antibodies targeting EGFR, such as cetuximab or panitumumab." (PMID 33519906, 2020). "We have also provided evidence for significant differences in EGFR protein expressions between primary and metastatic tumor tissue." (PMID 32155907, 2020). "The rationale for the application of anti-EGFR monoclonal antibodies in KRAS exon 2 wt MCC cases depended on the appropriate concordance of mutational status between primary and metastatic tumours, as presented in previous literature." (PMID 30683047, 2019). "The monoclonal antibody cetuximab, which displays EGFR extracellular domain-specific binding, has proven effective in the treatment of locally advanced disease and relapsed/metastatic disease." (PMID 31615015, 2019). "In conclusion, the overall discordance rates in EGFR mutation status between primary NSCLC and distant metastatic tumors is low but varied largely between studies." (PMID 31216329, 2019). "In this cohort, 8 of 74 patients with initially unresectable metastatic disease received anti-EGFR therapy with cytotoxic agents." (PMID 30792536, 2019). "Currently, most patients with EGFR mutant NSCLC receive a first- or second-generation EGFR TKI as primary therapy for metastatic disease." (PMID 30915273, 2019). "This cohort consisted of 30 mCRC patients with RAS wild-type tumors on tissue analysis that had received systemic anti-EGFR therapy during treatment for metastatic disease." (PMID 31597339, 2019). "Currently, the EGFR inhibitor cetuximab has been approved for HNSCC as a first-line treatment in patients with recurrent or metastatic disease." (PMID 29423074, 2018). "Despite their promise in the setting of metastatic disease, there is as yet insufficient evidence to conclude on a role for epidermal growth factor receptor (EGFR) inhibitors in locally advanced NSCLC." (PMID 29456881, 2018). "Deregulation of the EGFR pathway by overexpression or constitutive activation of this receptor can promote tumor progression, including metastatic disease." (PMID 29949609, 2018). "Some studies find that high concordance can be observed between the primary and metastatic tumours, suggesting that the detection of one lesion is sufficient to predict the response to EGFR-targeted therapy." (PMID 30171333, 2018). "Beyond metastatic disease, several studies addressed the relevance of EGFR status of CTCs in primary BC." (PMID 29229933, 2017). "In conclusion, this study provides additional support for comprehensive profiling in PT, which can identify several potentially targetable pathways including EGFR, angiogenesis, and immunotherapy for patients with locally advanced or metastatic tumors." (PMID 26625196, 2016). "There are clinical reports that have shown an up-regulated EGFR expression in both primary and metastatic tumors." (PMID 25940703, 2015). "EGFR can induce EMT in cancer cells by up-regulating Twist, and promoter methylation of EGFR has been detected in metastatic tumors from patients with CRC." (PMID 26101583, 2015). "These efforts proved fruitful as anti-EGFr treatments have been effective as single agent therapies or in combination with chemotherapy for patients with metastatic disease." (PMID 26458879, 2015). "The feasibility of EGFR testing was similar in different types of material, and in samples from primary versus metastatic tumors." (PMID 25086987, 2015).
metastatic disease (continued). "STAT3 represents a particular promising target in this tumor entity, because, especially for patients with recurrent or metastatic disease, RT can be combined with an EGFR inhibitor, as activation of EGFR signaling commonly stimulates STAT3 phosphorylation." (PMID 25268165, 2014). "Specifically, the number of lines of treatment for metastatic disease was reduced in the post-testing group (1.31 versus 2.04, p = 0.01), as was the use of EGFR inhibitors (17.0% versus 30.6%)." (PMID 24788807, 2014). "Accordingly, two antibodies, cetuximab and panatimumab, which selectively target the extracellular domain of the epidermal growth factor receptor (EGFR), have been approved for the treatment of metastatic diseases." (PMID 23565769, 2013). "Expression of 13 miRNA genes predicts response to EGFR inhibition in cancer cell lines and tumours, and discriminates primary from metastatic tumours." (PMID 22045191, 2012). "Recent attempts of treatment for unresectable or metastatic disease comprise targeted therapies against the epidermal growth factor receptor (EGFR, ErbB1) and the human epidermal growth factor receptor 2 (HER2, ErbB2)." (PMID 22240798, 2012). "Extensive research efforts focusing on the EGFR pathway in different solid tumor types have resulted in recent approval of a number of novel therapeutic agents for locally advanced as well as metastatic disease." (PMID 23320170, 2012). "There is strong evidence for considering EGFR mutation as a good predictive marker for response to an EGFR TKI and it is appropriate for these patients to receive treatment with an EGFR TKI for the treatment of metastatic disease." (PMID 22666589, 2012). "In the metastatic tumors averages of CNs for EGFR were 2.5 to 2.8 per cell with EGFR to CEP 7 ratios remaining below 2.0." (PMID 22691727, 2012). "Although data guiding this choice are lacking the purpose of the study was to assess the correlation between EGFR gene promoter methylation and clinical outcome in patients treated with cetuximab for metastatic disease." (PMID 21559018, 2011). "In the present study, by using immunofluorescence microscopy, we detected EGFR-positive CTCs in 38% and 44% of patients with early and metastatic disease, respectively, harboring CTCs in their blood." (PMID 18822183, 2008). "Among a total of 62 CTCs identified in patients with early disease, seven (12%) stained positively for both EGFR and CK, whereas the respective numbers for patients with metastatic disease were 68 (42%) out of 161 cells." (PMID 18822183, 2008). "The incidence of EGFR overexpression (grade 2+, 3+) was 26.5% in both primary and metastatic tumours." (PMID 19238633, 2008). "Epidermal growth factor receptor and K-RAS mutations were detected in the metastatic tumours of three (12%) and five (20%) patients, respectively." (PMID 19238633, 2008). "Three out of 16 (18.8%) primary and seven out of 16 (43.8%) metastatic tumours expressed phosphorylated EGFR (pY1173-EGFR-positive)." (PMID 19238633, 2008). "As EGFR-targeted treatment strategies are employed to treat metastatic disease on the basis of our data, only the EGFR-downstream signalling pathway status in metastases would be relevant." (PMID 17579627, 2007). "Over the past decade, EGFR targeted therapies have extended beyond metastatic disease into early-stage and locally advanced settings, as demonstrated by ADAURA, NeoADAURA, and LAURA studies, which established osimertinib as the standard of care therapy across disease stages." (PMID 41438982, 2025). "Interestingly, PT in patients with relatively early diagnosis of metastatic disease were enriched for hypoxic and EGFR+ tumor phenotypes." (PMID 39437149, 2025). "Like other oncogenes, EGFR mutation is associated with a higher rate of metastatic disease in the central nervous system compared to non-oncogene-addicted NSCLC." (PMID 40075878, 2025).
metastatic disease (continued). "Even if patients have poly-metastatic disease at the start of the initial therapy and if they have oligo-residual disease after 3–6 months of EGFR-TKI treatment, LAT for residual disease could be considered." (PMID 40647500, 2025). "This illustrates ACTL’s potential to remodel the tumor immune milieu and overcome osimertinib resistance of undefined etiology, in contrast to immune-checkpoint inhibitors, which show limited activity in EGFR-mutant advanced NSCLC but confer clear benefit in EGFR-wild-type metastatic disease." (PMID 41425254, 2025). "Features at the bottom of the plot, such as underweight pretreatment BMI, EGFR status, pre-existing metastatic disease, and immunotherapy with anti-PD-1 plus chemotherapy, showed minimal impact on the model’s predictions, as evidenced by their SHAP values nearing zero." (PMID 40636413, 2025). "Both GLUT1 and EGFR are most frequently expressed in both primary and metastatic tumors." (PMID 38831321, 2024). "The most common reasons for screen failure included no known EGFR mutations (52%) and metastatic disease (12%)." (PMID 38897205, 2024). "According to this study, aberrations in EGFR and KRAS were encountered in both primary and metastatic tumors, while certain mutations such as HRAS could only be traced to metastatic tumors." (PMID 38539567, 2024). "In early phase, multicentre trials (AURA and AURA2) in patients with locally advanced or metastatic disease, osimertinib demonstrated clinical activity in patients with EGFR exon 20 p.T790M, supporting its use in patients who have progressed on an EGFR tyrosine-kinase inhibitor." (PMID 36292049, 2022). "On the other hand, more and more reports seem to suggest the use of target drugs in metastatic disease, suggesting that cetuximab (an epidermal growth factor receptor (EGFR) inhibitor) may be useful in the treatment of advanced cSCC." (PMID 35456044, 2022). "Collectively, our analysis of single cell sequencing data suggested that the TME of primary tumor of NSCLC are enormously immunosuppressive than the metastatic tumor and are populated by high expression levels of EGFR/MAP2K1/MTOR/TEAD1/YAP1 within tumor microenvironment of NSCLC." (PMID 35655775, 2022). "With EGFR being the most relevant in the context of metastatic disease, the review will focus on the description of clinically pertinent mutations occurring within this tyrosine kinase receptor and the current and novel therapeutic approaches developed to date." (PMID 35806218, 2022). "The EGFR mutation status of metastatic tumors does not always coincide with that of the primary sites." (PMID 36457515, 2022). "For patients with metastatic disease, the outcome largely depends on the identification of a targetable driver such as EGFR, ALK, ROS1, ERBB2, BRAF, MET and more recently KRAS, RET, NRG1 and NTRK1-2-3, as mutations or gene fusions are highly predictive of response to matched targeted therapy." (PMID 35326552, 2022). "Impairment of DIAPH3 function may lead in wound healing process, which is linked to major signaling pathways involved in metastatic tumor growth, including EGFR, TGF‐beta, and FGFR, of which EGFR is a critical component." (PMID 35538918, 2022). "Among the 26 patients who were EGFR mutation-positive for the metastatic tumors, 17 (65%) were negative for the primary tumors." (PMID 36457515, 2022). "In the 24 EGFR wild-type and unknown patients, 7 had local tumor progression and 17 had metastatic disease." (PMID 34696229, 2021).
metastatic disease (continued). "Activated EGFR pathway signaling is known to support the growth of a subgroup of CRCs independent of their clinical stage and therefore more important for establishing the primary cancer growth and less critical for the development of the metastatic disease." (PMID 34271981, 2021). "This percentage was about the same among patients with metastatic disease at the time of EGFR-TKI treatment initiation [24.1% (21/87)], while it increased to 30.7% (27/88) among evaluable patients with metastatic disease at the time of progression in the first-line setting." (PMID 34202063, 2021). "Since these factors have been reported to correlate with survival of stage IV EGFR+ NSCLC patients, we examined whether this association might be affected by the setting of metastatic disease, i.e., de novo vs. secondary." (PMID 33898315, 2021). "Within the metastatic disease setting, the presence of KRAS/NRAS mutations provides resistance to cetuximab and panitumumab, while BRAFV600E mutation predicts response to anti-EGFR targeted therapies in combination with a BRAF inhibitor." (PMID 34201502, 2021). "All received single-agent PD-1 blockade with 37 (61%) in the first-line (1L) setting for advanced, incurable or metastatic disease and 24 (39%) in the second-line (2L) setting after chemotherapy and/or epidermal growth factor receptor (EGFR) inhibitor therapy use in the 1L." (PMID 32868898, 2020). "Similarly to primary tumors, the response of brain metastasis to EGFR inhibitors is better in patients with activating EGFR mutations while the activity of these drugs in individuals with wild-type EGFR metastatic disease is modest at best." (PMID 32434541, 2020). "In serum, EGFR mRNA levels were found to decline significantly following surgical resection in 56 patients with early stage NSCLC.In our patients, although serum EGFR mRNA declined in patients with metastatic as well as non-metastatic disease, the degree of decline was similar between both groups." (PMID 33247670, 2020). "In addition to its prognostic utility, RNAMethyPro also emerged as a robust predictor of response to anti-epidermal growth factor receptor (anti-EGFR) therapy in colorectal patients with metastatic disease." (PMID 31069256, 2019). "In this case, targeting the metastatic disease with an anti-EGFR agent may have improved the outcome for this patient." (PMID 29423054, 2018). "In cohort 2, there were also no statistical differences in the frequencies of EGFR T790M mutation and other GMs between 54 primary tumors and 53 unpaired metastatic tumors." (PMID 29518290, 2018). "It is possible that patients with metastatic disease may refuse treatments such as anti-EGFR therapy, rendering KRAS status of little clinical value." (PMID 29202108, 2017). "Overall, we put forth the hypothesis that fundamental changes in EGFR signaling between primary and metastatic tumors, a process we term the ‘EGFR paradox,’ contribute to the clinically observed inherent resistance to EGFRi." (PMID 28435746, 2017). "Until now EGFR has been the principal target with respect to development of new drugs, but might be necessary to know other alternative to the control of recurrent/metastatic disease and locally advanced stage." (PMID 26927178, 2016). "However, so far, only KRAS mutation analysis has been used clinically as a predictive marker for the efficacy of anti-epidermal growth factor receptor antibodies in metastatic disease." (PMID 25426562, 2015).
metastatic disease (continued). "The best approach to guide anti-EGFR treatment decision in SP-CRC with metastatic disease would be to test the metastatic tissue for KRAS and NRAS mutations, because it is not possible to be certain which primary SP-CRC lesion led to the metastasis without any additional study." (PMID 25859555, 2015). "Second, we were unable to demonstrate the intra-patient variability of the EGFR or KRAS mutations between primary lesions and metastatic lesions, because the tests for EGFR and KRAS mutations were performed in either the primary tumor or metastatic tumor sample from each patient." (PMID 26081767, 2015). "Therefore, radioiodinated PYK-SPECT is expected to allow visualization of primary and metastatic tumor lesions that express active mutant EGFR-TK." (PMID 23494210, 2013). "In squamous cell carcinoma of the head and neck, EGFR MoAbs are now an integral component of the standard of care, either in combination with radiotherapy for primary disease or with platinum-based chemotherapy for recurrent or metastatic disease." (PMID 23320170, 2012). "Although almost 70% of patients with NSCLC present with locally advanced or metastatic disease at the time of diagnosis, KRAS and EGFR mutation status is most commonly assessed only in the primary tumor tissue based on the assumption that primary and metastases are pathologically concordant." (PMID 21414214, 2011). "Majority of the discordant cases in our study showed KRAS and EGFR mutations in the metastatic tumors rather than in their corresponding primary tumors." (PMID 21414214, 2011). "In addition, three independent studies also showed discordance in the EGFR gene status of the primary tumor and corresponding metastatic tumor." (PMID 22108465, 2011). "Indeed, the knowledge of KRAS mutational status of a primary tumour is now mandatory for the treatment of metastatic disease, as it is a predictor of resistance to monoclonal antibodies of the epidermal growth factor receptor (anti-EGFR moAbs)." (PMID 20485284, 2010). "Indeed, EGFR activation was demonstrated in a higher proportion of patients with metastatic disease compared with patients with early disease." (PMID 18822183, 2008). "This phase 2 study was designed to evaluate the efficacy of mobocertinib 160 mg QD in Japanese patients with locally advanced or metastatic NSCLC whose tumors harbor EGFR exon 20 insertion mutations and who had not previously received systemic treatment for locally advanced or metastatic disease." (PMID 39190099, 2024). "In patients with metastatic disease and activating EGFR mutations treated with EGFR inhibitors, there was no numerical difference in progression-free survival between patients on first-generation (erlotinib and gefitinib) or third-generation (osimertinib) EGFR inhibitors." (PMID 37894716, 2023). "EGFR is overexpressed in approximately 80% of CRCs and correlates with increased propensity to metastasis and decreased patient survival and EGFR‐targeted therapeutic monoclonal antibodies, cetuximab and panitumumab, are approved for the treatment of metastatic disease." (PMID 34856074, 2022). "Likewise, the anti-EGFR free interval >16 months maintained the independent role for PFS (p = 0.020) among the significant variables in the univariate analysis (i.e., long anti-EGFR free interval, previous response to anti-EGFR treatment, and previous lines >2 for metastatic disease)." (PMID 35530345, 2022). "Of the 34 patients who had EGFR mutation-negative primary tumors, 6 (17.6%) developed a new EGFR mutation in the metastatic tumor (two with deletion mutations in exon 19, three with missense mutations in exon 21, and one with co-current mutations in exons 20 and 21)." (PMID 35912248, 2022). "The expression of the EGFR gene could be regulated by amplification mechanisms or a high frequency of polysomies, as is often observed in metastatic tumors, or by miRNAs (i.e., miRNA-134) in non-metastatic tumors." (PMID 32170146, 2020).